SIRT1 (sirtuin 1)
Diseases named in the same sentence as SIRT1 in open-access papers (continued):
Sharing a sentence is not in itself a finding about the gene and the disease.
cardiovascular diseases (continued). "Furthermore, several studies highlight Sirt1 and NAD+ levels as promising targets for treating metabolic and cardiovascular diseases." (PMID 39062955, 2024). "The results showed TFDM was the main active ingredient in DML and could exert therapeutic effects on cardiovascular diseases through the NOX-4/ROS/p38 MAPK, Bcl-2/Bax and AMPK/SIRT1/PGC-1α signalling pathways." (PMID 38169375, 2024). "SIRT1 is the well-studied family member of NAD+-dependent deacetylase, which could protect against cardiovascular diseases." (PMID 35722093, 2022). "The expression of SIRT1 is associated with lifespan and is reduced with aging both in animal models and in humans, where the lack of SIRT1 is regarded as a potential mediator of age-related cardiovascular diseases." (PMID 34690807, 2021). "According to our results, acute short-term hypoxia might play an important additional role in the dysregulation of sirtuins, namely of SIRT1 and SIRT4, in cardiovascular disorders." (PMID 32796661, 2020). "Sirtuin 1 (SIRT1), a class III HDAC, regulates endothelial nitric oxide synthase (eNOS), is disrupted by oxidative stress and systemic inflammation, and involved in different aspects of cardiovascular disease, aging and stress resistance." (PMID 31208080, 2019). "Regarding the progress and development of cardiovascular disease, mice lacking SIRT1 gene show greater injury following ischemia-reperfusion process and this injury is reduced in SIRT1 transgenic mice." (PMID 29415476, 2018). "Silent information regulator 1 (SIRT1), one of the sirtuin family distinguished by holding a highly conserved nicotinamide adenine dinucleotide- (NAD+-) binding catalytic domain, is deemed to be responsible for the beneficial effects in the development and treatment of cardiovascular diseases." (PMID 33062139, 2020). "However, the therapeutic indications of resveratrol mainly target diabetes and cardiovascular diseases rather than bone-related diseases, and since resveratrol is not a specific agonist of SIRT1, its multiple off-target effects are a key factor to be considered." (PMID 39199358, 2024). "Western blot analysis confirmed that the level of endogenous SIRT1 protein was severely reduced by overexpression of MIR34A, while the level of exogenous SIRT1 protein was not affected, which delayed the aging process in cardiovascular diseases." (PMID 37805704, 2023).
infection (118 papers, 2012 to 2026). The state of being infected such as from the introduction of a foreign agent such as serum, vaccine, antigenic substance or organism. "Autophagy in caprine EECs induced by N. caninum infection was previously found by our group, and previous studies showed that SIRT1 was related to cell autophagy during inflammations and pathogenic infections." (PMID 35915458, 2022). "SIRT-1 is expression is also reduced following Mycobacterium tuberculosis infection and global SIRT-1−/− mice exhibit an elevated susceptibility to infection." (PMID 34485381, 2021). "We have reported previously that celecoxib, a non-antibiotic agent in combination with an antibiotic (ampicillin) managed infection and inflammation caused due to S. aureus in macrophage model via activation of SIRT1, a master regulator of inflammation." (PMID 28533769, 2017). "Overall, the high correlation of AMPK and SIRT1 activities with parasite burden in in vivo infections underlines a new and high biologically relevant role for a metabolic control by the parasite." (PMID 25738568, 2015). "Our results show that SIRT1 activation can preserve RGCs and reduce axonal loss following infection with MHV." (PMID 24383546, 2014). "SIRT1 inhibition is also reported to be associated with a higher bacterial load during infection." (PMID 38770241, 2024). "We found that infection is associated with the activation of AMPK downstream to SIRT1 and LKB1." (PMID 25738568, 2015). "Increased promoter recruitment of p50, HDAC1, HDAC2 and Sirt1 to the NF-kB-associated site A region of the mir-424-503 gene was found in cells following infection, as assessed by ChIP analysis using primers covering the NF-kB-binding region within the promoter." (PMID 23724129, 2013). "Moreover, SIRT1-deficient dendritic cells drive Th1 immune responses and microbial inflammation, suggesting that SIRT1 is involved in T cell differentiation during infection." (PMID 36139497, 2022). "Quantitative assessment of intracellular MAB confirmed that ex‐527 compromised the capacity of SIRT1‐treated macrophages to effectively combat infection." (PMID 41085014, 2026). "Herein, we show that MVC infection markedly upregulates the mRNA and protein expression levels of SIRT1 in a time-dependent manner." (PMID 41901696, 2026). "Conversely, other findings suggested that SIRT1 expression is upregulated following infection, and supplementation with large amounts of mtNLS-Sirt1 significantly inhibits viral replication." (PMID 40006932, 2025). "Previous studies on EV-A71 infection have reported a decrease in SIRT1 levels, accompanied by an increase in reactive oxygen species (ROS)." (PMID 40006932, 2025). "Meanwhile, the expressions of Slc11a1, Havcr2, Ccl12, Sirt1, Ifng, Ccl3, and Trem2 were higher during the whole infection process." (PMID 40170749, 2025). "SIRT1 regulates responses during infections by modulating immune defenses and/or controlling inflammation." (PMID 41416347, 2025). "Immunofluorescence results showed that EV-D68 infection induced SIRT1 subcellular translocation from the nucleus to the cytoplasm." (PMID 40006932, 2025). "Following infection, SIRT1 orchestrates immune, inflammatory, autophagic, and metabolic responses, all required to establish and control host defenses." (PMID 41416347, 2025). "Plasmids expressing SIRT1 (pBudCE4.1-SIRT1) or a control plasmid (pBudCE4.1) were transfected into 293T cells, followed by infection with EV-D68." (PMID 40006932, 2025). "The results showed that SIRT1 expression increased proportionally with the multiplicity of infection (MOI) and the duration of post-infection time, indicating that EV-D68 infection induces SIRT1 expression." (PMID 40006932, 2025). "Conversely, rescue of SIRT1 expression in SIRT1‐KO VSMCs by infection of Ad‐SIRT1 abolished PDGF‐BB‐induced phenotypic switching, compared with Ad‐GFP group." (PMID 40242156, 2025).
infection (continued). "This indicates that SS-a effectively inhibits infection by promoting the expression of SIRT1, Nrf2, and HO-1 in mammary tissue, thereby activating the SIRT1/Nrf2 signaling pathway." (PMID 41011202, 2025). "As expected, si-Drp1 and si-SIRT1 interfered with DEX’s effect to improve mitochondrial morphology during LPS infection." (PMID 39455916, 2024). "(G) Serum IL- 6 levels of STM- infected C57BL/6 WT mice (males) mice treated with SIRT1(EX- 527) or SIRT3 (3TYP) inhibitors or SRT1720 (SIRT1 activator) at 1 mg/kg dosage on fifth day post- infection." (PMID 39693143, 2024). "This altered host metabolism upon Sirt1 and Sirt3 knockdown condition influences the outcome of infection by regulating the intracellular bacterial metabolism, which shows reduced bacterial glycolysis and increased FAO." (PMID 39693143, 2024). "Knockdown of Sirt1 or Sirt3 in infected RAW 264.7 macrophages resulted in a reduction in anti-inflammatory CD206 surface marker expression at 16 hr post-infection." (PMID 39693143, 2024). "(D, E) Lactate estimation assay of S. Typhimurium-infected RAW 264.7 macrophages upon Sirt1 (D) or Sirt3 (E) knockdown condition at 16 hr post-infection." (PMID 39693143, 2024). "(E) Bacterial load in blood at different days post- infection upon SIRT1 or SIRT3 inhibition at 1 mg/kg dosage in C57BL/6 mice (males)." (PMID 39693143, 2024). "Upon infection of RAW 264.7 murine macrophages with wildtype S. Typhimurium strain 14028S, we observed an increased expression level of Sirt1 and Sirt3 at initial and middle phases of infection, precisely at 2 hr and 6 hr post-infection through qPCR." (PMID 39693143, 2024). "(C) Quantitative representation of flow cytometric analysis of M2 surface marker CD206 in STM-infected Sirt1 or Sirt3 knockdown RAW 264.7 macrophages in comparison to the scrambled control at the indicated time post-infection." (PMID 39693143, 2024). "(I) qPCR-mediated expression of Sirt1 in RAW 264.7 macrophages upon infection with wildtype S. Typhimurium or SPI-1 (∆invC)or SPI-2 (∆ssaV and ∆steE) mutants of S. Typhimurium." (PMID 39693143, 2024). "(B) In vivo organ burden of STM upon SIRT1 or SIRT3 inhibition in C57BL/6 mice on fifth day post- infection under specified dosage of inhibitor treatment." (PMID 39693143, 2024). "(F) Bacterial load in blood on fifth day post- infection upon SIRT1 or SIRT3 inhibition at 1 mg/kg dosage in C57BL/6 WT mice (males) and cybb-/- (males) mice." (PMID 39693143, 2024). "(E) Representative confocal images of RAW 264.7 macrophages exhibiting SIRT1 expression upon S. Typhimurium infection at indicated time points post-infection." (PMID 39693143, 2024). "Further, the knockdown of Sirt1 resulted in increased acetylation status of the NF-κB p65 upon infection in comparison to the scrambled, infected control." (PMID 39693143, 2024). "Upon detection of extracellular ROS generation through phenol red hydrogen peroxidase assay, we detected higher ROS generation upon Sirt3 KD at 6 hr post-infection and greater ROS production at 16 hr and 20 hr time points in Sirt1 knockdown macrophages." (PMID 39693143, 2024). "We found that SIRT1 knockdown showed increased acetylation of HIF1α in the infected macrophages in comparison to the scrambled infected control at 16 hr post-infection." (PMID 39693143, 2024). "Compared with the LPS group, si-Drp1 + LPS and DEX + LPS groups had decreased fragmentation and increased mitochondrial length (p < 0.01), and DEX-treated LPS infection with si-SIRT1 or si-PGC-1α exhibited decreased fragmentation in NRK-52E cells." (PMID 39455916, 2024). "(C) In vivo organ burden of STM upon Sirt1 or Sirt3 adenovirus-mediated in vivo knockdown in C57BL/6 mice on fifth day post-infection." (PMID 39693143, 2024). "On one hand, the body needs to respond quickly to harmful stimuli such as an infection or tissue damage by switching to a rapid energy generation system through suppressing SIRT1." (PMID 38041753, 2024).
infection (continued). "Results depicted significant enhancement in the production of ROS at 16 hr post-infection upon knockdown of Sirt1 or Sirt3 in comparison to untransfected or scrambled control." (PMID 39693143, 2024). "The result was promising due to the uptake of B. abortus in the cells upon pre-incubation with anti-sirtuin-1 antibody being inhibited at 0 h post-infection." (PMID 39770737, 2024). "(D) Representation of splenic length of STM- infected spleen tissue harvested from C57BL/6 mice (males) on fifth day post- infection upon SIRT1 or SIRT3 inhibition at 1 mg/kg dosage." (PMID 39693143, 2024). "Further, MTT assays showed that the ability of apigenin to sustain cardiomyocyte viability in the presence of Dox was inhibited once infection with si/Sirt1." (PMID 37928261, 2023). "We observed that EV-D68 infection induces relocalization of SIRT-1 from the nucleus to the cytosol starting at 3 hpi." (PMID 37850626, 2023). "We then examined the effect of SIRT-1 depletion and EV-D68 infection on SERCA2A protein levels by western blot." (PMID 37850626, 2023). "Our data show that a portion of nuclear SIRT-1 relocalizes to the cytosol upon infection by EV-D68 and PV (, 5A)." (PMID 37850626, 2023). "Previous studies revealed that murine macrophages infected by T. gondii showed dynamic alterations in the levels of histone deacetylase SIRT1 with an increase in the duration of infection." (PMID 36466662, 2022). "Following infection with Cryptosporidium parvum, a zoonotic protozoan parasite, the expression of let-7i decreased, but SIRT1 levels in human biliary epithelial cells increased." (PMID 36139497, 2022). "Below, we discuss more detailed roles of SIRT1 in the past and recent studies of various infections." (PMID 36139497, 2022). "The results revealed that the infection led to an increased translocation of SIRT1 in the host cell cytoplasm from the nucleus as well as an upregulated activity of lysosome." (PMID 36466662, 2022). "During infection with Gram-positive Staphylococcus aureus, SIRT1-mediated regulation of IL-9 was shown to modulate inflammatory responses induced by the bacterium." (PMID 36139497, 2022). "Among the SIRTs, SIRT1 is the most well-studied, with a role in the modulation of immune and inflammatory responses following infection." (PMID 36139497, 2022). "Additional studies on the role of SIRT1 in various infection routes and strains of T. gondii and in immune cells important in Toxoplasma infection (e.g., neutrophils and dendritic cells) are needed." (PMID 36362370, 2022). "We previously identified mir142 as a critical contributor to the collapse of Sirt1 transcription and function in macaques that develop neuropathology as a result of infection with the Simian Immunodeficiency Virus." (PMID 36227148, 2022). "Among the SIRTs, SIRT1, which is critically involved in host defense against various infections, has been the most extensively studied." (PMID 36139497, 2022). "Infection with the parasite Leishmania donovani triggers SIRT1 induction to inactivate forkhead box O (FOXO)-1 through deacetylation, thus favoring parasite survival in host cells." (PMID 36139497, 2022). "The age-associated decrease in the expression of miR-181a in T cells has been linked to the miR-181a targeting activity of SIRT1, implying a role for SIRT1 in cell replication stress and delayed viral clearance during infection in older adults." (PMID 36139497, 2022). "Understanding the function of SIRT1 in balancing immune homeostasis will contribute to the development of new therapeutics for the treatment of infection and inflammatory disease." (PMID 36139497, 2022). "In HSV-1 infection of mice neuronal cultures, HSV-1 modulates the AMPK/Sirt1 axis differentially during infection, interfering with proapoptotic signaling and regulating mitochondrial biogenesis." (PMID 34066434, 2021).
infection (continued). "HSV-1 modulates the AMPK/Sirt1 axis differentially during the course of infection, interfering with proapoptotic signaling and regulating mitochondrial biogenesis." (PMID 34066434, 2021). "SIRT-1 regulates the expression and activity of ACC-1 and FASN, key enzymes involved in fatty acid biosynthesis that were upregulated in SIRT-1 absence following infection." (PMID 34485381, 2021). "Lv-SIRT1 infection increased SIRT1 mRNA by 5.28±0.33 folds (p<0.0001) and Lv-miR-217 increased miR-217 by 8.43±1.12 folds (p=0.001) at 72 h after infections." (PMID 32267139, 2020). "Western blot analysis showed that the expression of hsa-miR-217 inhibited SIRT1 expression in PC-14/B cells (p=0.0.50 vs control) and that Lv-SIRT1 infection increased SIRT1 protein level (p<0.0001 vs control)." (PMID 32267139, 2020). "In vivo models of CD show that administration of a SIRT1 activator (SRT1720) suppresses oxidative stress and inflammation associated with chronic Tc infection." (PMID 33330467, 2020). "The expression of Ifnβ was similar in the earlier time points but by 24 hr post infection Sirt1-/- DC showed significantly less expression." (PMID 32106265, 2020). "It has been shown that a lowered expression of regulatory proteins like TRIB3 (negative regulator of NF-kappaB signaling) and SIRT1 (anti-aging and anti-inflammatory) amongst aged/older individuals, rendering them more prone to infection." (PMID 32528233, 2020). "The expression of green fluorescent protein in PC-14/B cells at 72 h post-infection (Lv-miRNA-217 and/or Lv-SIRT1, MOI=10) was observed under the inverted fluorescent microscope." (PMID 32267139, 2020). "We have shown that SIRT1 transcription is suppressed by active infection and that this decrease is a key factor in the development of long-term disruptions in the regulation of gene expression, with resulting aging-like phenotypes." (PMID 32283831, 2020). "Instead, it appears that PARP1 and SIRT1 balance the Mo/Mφ role for removal of cellular debris produced by Tc infection and prevent further tissue damage while promoting healing." (PMID 31905606, 2019). "We monitored infection by RT-qPCR and found that SIRT1 mutants displayed reduced infection and that the level was further reduced upon treatment with sirtinol." (PMID 31289184, 2019). "We also found that this dependency is evolutionarily conserved, as adult flies treated with sirtuin inhibitors show decreased infection, and this is exacerbated in SIRT1 or SIRT2 mutants." (PMID 31289184, 2019). "In cultured MLO-Y4 cells, infection of TSC1 shRNA lentivirus significantly induced Sirt1 expression and accelerated Sost promoter H3K9 acetylation, while rapamycin treatment reduced Sirt1 levels." (PMID 31088250, 2019). "The kinase MAPK1 and protein SIRT1 both presented a significant lower transcription only 24 h post infection, when most living cells presumably are in apoptosis process." (PMID 29813068, 2018). "Within avulsed MNs, infection with AAVrh10-GFP did not change the nuclear ring-like pattern of SIRT1 expression induced by RA, but infection with AAVrh10-SIRT1 led to accumulation of SIRT1 predominantly in the cytoplasm of MNs, similar to NeuroHeal’s effect." (PMID 29382857, 2018). "At later phases of infection, Tat inhibition of SIRT1 appears to be critical for inducing cell transformation and apoptosis." (PMID 29449904, 2018). "During the infection, SIRT1 activity was depressed in the heart, and SIRT1 agonist treatment improved its activity along with left-ventricular function, although it did not significantly affect cardiac remodeling or interstitial fibrosis." (PMID 29672619, 2018).